WNT5A (Wnt family member 5A)
Diseases named in the same sentence as WNT5A in open-access papers (continued):
Sharing a sentence is not in itself a finding about the gene and the disease.
gastric cancer (continued). "Within the group of upregulated molecules, different Wnt molecules are enhanced in gastric cancer: For example, Wnt5A has been shown to be significantly upregulated, and histological analyses revealed that this upregulation occurs in 30% of gastric carcinomas." (PMID 31248166, 2019). "We examined nearly 200 specimens using an antibody already confirmed accurate in immunohistochemical analysis of Wnt5a-positive gastric cancers." (PMID 29765514, 2018). "Wnt5a expression correlates significantly with malignancy and stage of progression in malignant melanoma, gastric cancer, prostate cancer, lung cancer, and pancreatic cancer." (PMID 29765514, 2018). "Cell motility in Wnt5a-positive gastric cancer is increased through activation of FAK and Rac to induce malignant transformation." (PMID 29765514, 2018). "WNT signaling plays an important role in gastric cancer development, especially WNT5A, a member of the WNT family of secreted lipid-modified glycoproteins, was closely related to the gastric cancer invasion and metastasis." (PMID 30405404, 2018). "Wnt5a was found to be up-regulated in solid tumors, like pancreatic cancer, skin cancer, and gastric cancer." (PMID 29054966, 2017). "Down-regulation of PI3K/Akt/GSK3β signaling in gastric cancer cells suppresses Wnt5a-induced activation of RhoA and cell migration." (PMID 29213214, 2017). "Wnt5a is highly expressed in gastric carcinoma wherein it has been shown to activate the small GTP-binding protein Rac, which in turn activated focal adhesion kinase (FAK) and paxillin, main regulators of cell migration." (PMID 27571105, 2016). "In gastric carcinoma, Wnt5a secreted by Cxcr4+ gastric innate lymphoid cells (ILCs) in the perivascular gastric stem cell niche enhanced the colony formation ability of Mist1+ gastric stem cells." (PMID 27571105, 2016). "In this study we generated an anti-Wnt5a monoclonal antibody (mAb5A16) from a phage library; this antibody inhibited invasion and metastasis of gastric cancer cells both in vitro and in vivo." (PMID 25622531, 2015). "To date, only a few factors have been described to regulate Wnt5a expression during gastric cancer progression." (PMID 25779663, 2015). "Together, in the present study, we uncovered an essential role of Wnt5a in regulating EGF-induced gastric cancer cell EMT." (PMID 25779663, 2015). "We here provide evidence that Wnt5a is a downstream mediator of EGF signaling in gastric cancer cells suggesting a primary effect of Wnt5a on reducing gastric cancer cell EMT." (PMID 25779663, 2015). "In the present study, we provide evidence that inhibition of Wnt5a expression is essential for EGF-induced EMT program in gastric cancer cells." (PMID 25779663, 2015). "Analysis of gastric cancer specimens revealed an inverse correlation between P-ERK and Wnt5a protein levels and an association between Wnt5a expression and better prognosis." (PMID 25779663, 2015). "Together, these data point to the ability of Arf6/ERK-dependent mechanism that leads to increased EGF-induced EMT of gastric cancer cells by inhibiting Wnt5a transcriptional expression." (PMID 25779663, 2015). "The authors further demonstrated that Wnt5a had the ability to stimulate cell migration and invasion in gastric cancer cells." (PMID 24944588, 2014). "Second, Wnt5a overexpression and exogenous Wnt5a treatment elevated MCP-1 expression in gastric cancer cells." (PMID 24993819, 2014). "The positive rate of Wnt5a expression in stage III/IV gastric cancer tissues (49.5%) was significantly higher than that in stage I/II gastric cancers (13.8%)." (PMID 24944588, 2014). "The results revealed that the expression of Wnt5a was upregulated in 30% (71/237) of patients with gastric cancer, which positively correlated with the T grade (depth of invasion) and N grade (degree of lymph node metastasis)." (PMID 24944588, 2014). "The aim of this study is to reveal the involvement of Wnt5a in macrophage recruitment in gastric cancer." (PMID 24993819, 2014).
gastric cancer (continued). "On the other side, we silenced Wnt5a expression in Wnt5a-positive gastric cancer cell line MKN-45 with Wnt5a siRNA vector." (PMID 24993819, 2014). "Wnt5a was overexpressed in gastric cancer tissues, and correlated with monocyte chemotactic protein 1 (MCP-1) and interleukin 1β (IL-1β), respectively." (PMID 24993819, 2014). "Conditioned medium from gastric cancer cells transfected with Wnt5a stimulated macrophage chemotaxis and cytoskeletal changes via MCP-1, which were suppressed by recombinant IL-1 receptor antagonist (rIL-1Ra)." (PMID 24993819, 2014). "Wnt5a has been found to be upregulated in several solid tumors, such as gastric cancer and skin cancer." (PMID 24156409, 2013). "Antibody-mediated suppression of Wnt5a activity results in the prevention of metastasis of gastric cancer cells." (PMID 24156409, 2013). "Kurayoshi and co-workers examined the effects of Wnt-5a on MKN-1 gastric cancer cell migration and invasion." (PMID 24310428, 2011). "Wnt5a, a ligand associated with the non-canonical pathway, has been implicated in promoting the invasion and migration of gastric cancer cells." (PMID 39936971, 2025). "The positive correlation between RUNX3 and WNT5A expression could therefore be commonly observed in gastric cancer." (PMID 38240752, 2024). "However, a tumor suppressive role also been reported for GPX3 in gastric cancer wherein its knockdown resulted in tumor cell invasion and migration by targeting NFкB/Wnt5a/JNK signaling." (PMID 36389725, 2022). "Antagonizing Wnt5a in CAF can inhibit gastric-cancer-cell growth and migration." (PMID 35884514, 2022). "MiR-26a-5p level was low in the gastric cancer and overexpressed miR-26a-5p could promote cell apoptosis, suppress cell proliferation and invasion by inhibiting Wnt5a expression in gastric cancer cells." (PMID 35948893, 2022). "Intriguingly, Yap/Taz is modulated by WNT5A, suggesting that FZD5 signaling may be suppressed by WNT5A in gastric cancer." (PMID 33618713, 2021). "Furthermore, we found an overexpression of ITGA2, which regulates Metastases and EMT, LAMC2 and WNT5A genes, that mediate invasion of gastric cancer cells." (PMID 34012923, 2021). "Disheveled, a scaffolding protein with crucial roles in Wnt signaling, mediates the adhesion-related effects of Wnt5a in gastric cancer cells, and several studies provide growing support for a model whereby Disheveled-interacting proteins mediates Wnt5a signaling to modulate cytoskeleton dynamics." (PMID 32195251, 2020). "In gastric cancer, Wnt5a promotes invasion and migration by modulating integrin adhesion turnover." (PMID 32195251, 2020). "This review summarizes available research about Wnt5a expression and signaling in gastric cancer." (PMID 32195251, 2020). "Instead, this review focuses on the specific role of Wnt5a in gastric cancer." (PMID 32195251, 2020). "However, our data are in contrast with a report on gastric cancer cells in which the authors suggest that reduced Rac1 activity explains why a WNT5A antibody impairs the migration and invasion of these cells." (PMID 30582770, 2019). "The anti-gastric cancer mechanism of BBR might be involved in AMPK- HNF4α-WNT5A signaling pathway and HNF4α is a key molecule target." (PMID 30405404, 2018). "Knockdown of WNT5A reduced the metastasis ability of gastric cancer cells." (PMID 30405404, 2018). "Wnt5a may play an important role in constructing an advantageous tumor microenvironment for the progression and development of human gastric carcinoma." (PMID 29054966, 2017). "Administration of anti-WNT-5A antibody attenuates liver metastases of gastric cancer cells in vivo." (PMID 26514730, 2016). "Similarly, WNT-5A induces migration in gastric cancer cells by activating PI3K/AKT pathway which phosphorylates and inactivates GSK-3β and activates RhoA leading to cytoskeleton remodeling." (PMID 26514730, 2016). "LAMC2 (Laminin γ2) mediated the Wnt5a-induced invasion of gastric cancer cells." (PMID 27534621, 2016).
gastric cancer (continued). "Moreover, another study showed that Wnt5a induced gastric cancer migration and invasion through binding to Fzd2 and Ror2, leading to their internalization in a clathrin-dependent manner." (PMID 27571105, 2016). "More important, using ChIP and luciferase reporter assays, we were able to verify the importance of ERK within the nucleus, that is, through its direct binding to Wnt5a promoter, ERK negatively regulates Wnt5a transcriptional expression and serves as a master enforcer of gastric cancer cell EMT." (PMID 25779663, 2015). "Based on the analysis of a limited set of 50 gastric cancer cases, we found that the Wnt5a expression level was markedly reduced in poorly differentiated tumor tissues when compared with the well-differentiated tumor tissues, while P-ERK levels were in a reversed pattern." (PMID 25779663, 2015). "We hypothesized that P-ERK might also be involved in the down-regulation of Wnt5a in gastric cancer cells in response to EGF." (PMID 25779663, 2015). "Whether Wnt5a can influence the progression of gastric cancer cell by promoting EMT, however, is largely unknown." (PMID 25779663, 2015). "Overall, our clinical data support our in vitro data that Wnt5a may function to oppose gastric cancer progression and ERK may play a role as a Wnt5a repressor." (PMID 25779663, 2015). "In previous study, wnt5a expression showed aggressive behavior in breast or gastric cancer." (PMID 24564183, 2014). "In addition, the positivity of Wnt5a expression correlated with advanced stages and poor prognosis of gastric cancer." (PMID 24944588, 2014). "Our results demonstrate that Wnt5a induces MCP-1 production in gastric cancer, which is mediated by IL-1β, suggesting that Wnt5a is involved in macrophage recruitment, and IL-1Ra may be used to inhibit macrophage recruitment in gastric cancer." (PMID 24993819, 2014). "In gastric cancer cells, Wnt5a induced MCP-1 expression, which was mediated by IL-1β." (PMID 24993819, 2014). "Our study indicates that macrophage is another source of COX-2/PGE2 in gastric tissues, and Wnt5a may attribute to gastric cancer initiation via upregulating COX-2/PGE2 in macrophages." (PMID 24416340, 2014). "Our results demonstrate that Wnt5a is an inducer of MCP-1 in gastric cancer cells." (PMID 24993819, 2014). "A recent study showed that an anti-Wnt5a polyclonal antibody (pAb5a-5) inhibited the activation of Rac1 and the expression of laminin γ2, which decreased Wnt5a-dependent internalization of the receptor, thereby suppressing the metastasis of gastric cancer cells." (PMID 24944588, 2014). "In addition, Wnt5a promoted the migration of gastric cancer cells via the phosphatidylinositol 3-kinase/protein kinase B/GSK-3β/RhoA signaling pathway." (PMID 24944588, 2014). "First, Wnt5a expression was correlated with MCP-1 expression in gastric cancer tissues." (PMID 24993819, 2014). "As a member of noncanonical Wnt family, Wnt5a has been implicated in human malignancies, including gastric cancer." (PMID 24416340, 2014). "We investigated whether RUNX3 upregulates WNT5A in other gastric cancer cell lines." (PMID 38240752, 2024). "For example, activated YAP is involved in the intercellular communication between lymph node metastasis-derived gastric cancer cells (LNM-GC) and infiltrated mesenchymal stem cells (BM-MSCs) via exosomal Wnt5a." (PMID 36924251, 2023). "However, how gastric cancer cells can respond to WNT5A signaling remains unclear, given that the main receptor, ROR2, is commonly down-regulated in these cells." (PMID 37722040, 2023). "However, Wnt5a might induce other effects in gastric cancer cells, such as cell survival and induction of gene expression." (PMID 32195251, 2020).
gastric cancer (continued). "Emerging evidence has demonstrated that Wnt/β‐catenin is activated after gastric cancer and plays a critical role in promoting invasion and migration through overexpressing or increasing the functions of several components of the Wnt pathway such as Wnt1, Wnt2, Wnt3, Wnt5a, Fzd‐3, CTNNB1 and LRP6." (PMID 28994231, 2018). "The anti-gastric cancer mechanism of BBR might be involved in AMPK-HNF4α-WNT5A signaling pathway." (PMID 30405404, 2018). "Indeed, Wnt5a regulates gastric tumour progression, whilst Wnt5a-Ror2 regulates mesenchymal stem cells to promote the growth of gastric cancer cells, suggesting this pathway may also regulate gastric stem cells." (PMID 29570681, 2018). "Additionally, WNT-5A abundance correlates with the expression of MCP-1 and IL-1β in gastric cancer tissues indicating that WNT-5A may drive macrophage infiltration and tumor-related inflammation." (PMID 26514730, 2016). "Furthermore, an anti-Wnt5a antibody inhibited liver metastasis of gastric cancer cells in vivo." (PMID 27571105, 2016). "Hence, it is worthwhile to determine the role of Wnt5a on the gastric cancer EMT." (PMID 25779663, 2015). "Therefore, Wnt5a overproduction and SFRP5 deficiency in gastric mucosa may together play an important role in gastric cancer initiation." (PMID 24416340, 2014). "Therefore, the expression of Wnt5a in gastric cancer cells may be critical for the migration and invasion of cancer cells from primary regions." (PMID 24944588, 2014). "Thus, the expression of Wnt5a correlates with the aggressiveness of the gastric cancer." (PMID 24944588, 2014). "The spreading of the receptor can explain how gastric cancer cells, low in ROR2, can respond to a WNT5A-high microenvironment and change into an invasive phenotype." (PMID 37722040, 2023). "In gastric cancer and glioma, RYK promotes cell migration and invasion whereas in prostate cancer Wnt5a-RYK have pro-apoptotic and pro-proliferative action." (PMID 36471440, 2022). "miR-876-5p targets WNT5A and MITF mRNA 3′UTR, represses the proliferation and migration ability of gastric cancer cells." (PMID 33542193, 2021). "A study in lymph node metastatic (LNM) gastric cancer focused on the roles of LNM-derived gastric cancer cells (LNM-GCs) in the education of BM-MSCs and identified exosomal Wnt5a as the key protein mediating BM-MSC reprogression by LNM-GCs." (PMID 34513701, 2021). "In the human gastric cancer cell line SGC-7901, suppression of PI3K/Akt/GSK3β pathway, and hence, activation of GSK3β inhibited Wnt family member 5A (Wnt5A)-induced activation of RhoA." (PMID 34440861, 2021). "The regulation of EMT by the Wnt signaling pathway has been determined including Wnt5a, FOXP3, SERPINH1, CUL4B, and SUFU, which can be used in BLCA, gastric cancer, and pancreatic cancer." (PMID 34579753, 2021). "WNT5A, a member of the WNT family, played an important role in gastric cancer invasion and metastasis." (PMID 30405404, 2018). "While WNT5A/ROR2 signaling acts tumor suppressive in hepatocellular carcinoma, gastric carcinoma, and myelogenous leukemia, it enhances proliferation of chronic lymphocytic leukemia." (PMID 29930766, 2018). "In gastric cancer cells, down-regulation of PI3K/Akt/GSK3β signaling in SGC-7901 cells suppressed Wnt5a-induced activation of RhoA." (PMID 28289332, 2017). "We noticed that some studies showed that Wnt5a increased migration and aggressiveness of gastric cancer cell lines such as MKN-7 and MKN-74 established in Japan, so it is possible that the effect of Wnt5a on EMT is gastric cancer cell-type dependent." (PMID 25779663, 2015). "Here, we show that downregulation of Wnt5a mRNA and protein by EGF is necessary for EGF-induced EMT in gastric cancer SGC-7901 cells." (PMID 25779663, 2015). "Therefore, the role of Wnt5a in gastric cancer may be more complicated than we have known." (PMID 24993819, 2014).
gastric cancer (continued). "Spearman’s rank correlation test was used to analyze the correlation among Wnt5a, MCP-1 and IL-1β in gastric cancer tissues." (PMID 24993819, 2014). "To explore the role of Wnt5a overexpression in macrophage recruitment, we investigated the effect of Wnt5a on the expression of MCP-1, a chemoattractant for macrophages, in gastric cancer cell lines." (PMID 24993819, 2014). "Overexpression of Wnt5a and downregulation of SFRP5, a Wnt5a antagonist, were both observed in gastric cancers recently." (PMID 24416340, 2014). "To confirm the stimulatory effect of Wnt5a on MCP-1 expression, we next transfected another gastric cancer cell HGC-27 with pcDNA3.1-Wnt5a." (PMID 24993819, 2014). "Ligands such as Wnt2, WNT5A, and WNT10B are involved in the EMT in gastric cancer." (PMID 38952556, 2024). "Also, we found that CAF2 up-regulated Wnt signaling pathway genes such WNT2 and WNT5A while down-regulating the expression of Wnt signaling inhibitor SFRP1, which was consistent with findings from the research on CAFs for gastric cancer." (PMID 39256364, 2024). "In agreement with our results, the aberrant methylation of other genes involved in the Wnt signaling pathway (e.g., WNT5A and WNT7A) has previously been described in tumor cells from the BC luminal subtype and in other tumor types, such as gastric cancer or chronic lymphocytic leukemia." (PMID 36393855, 2022). "The β-catenin-independent branch plays a similarly important role in cancer progression: the key ligands Wnt5a and Ror2 are upregulated in various gastric cancers, regardless of the histological phenotype." (PMID 30060804, 2018). "The prototypical ‘non-canonical’ Wnt, Wnt5a, which is synonymous with Wnt/β-catenin inhibition and promotion of cell motility and migration, is overexpressed in gastric cancer and correlates with poor outcome." (PMID 29570681, 2018). "On the other hand, Wnt5a is a potential suppressor of EMT in gastric cancer, wherein epidermal growth factor (EGF) activation of EMT required suppression of Wnt5a expression through activating ADP-ribosylation factor (Arf6), which binds to and represses the Wnt5a promoter." (PMID 27571105, 2016). "Accordingly, we speculated that EGF/Arf6 signals might be able to repress Wnt5a transcription directly, thereby allowing EMT in gastric cancer cells." (PMID 25779663, 2015). "To investigate whether our experimental findings could be relevant to the pathogenesis and progression of gastric cancer in humans, we examined Wnt5a and P-ERK expression patterns in gastric cancers with varied degrees of differentiation." (PMID 25779663, 2015). "Real-time PCR was used to determine Wnt5a mRNA level in 36 gastric cancer specimens and matched adjacent non-malignant tissues." (PMID 24993819, 2014). "SFRP5 expression was frequently downregulated in gastric cancer due to SFRP5 gene hypermethylation, which was hypothesized to lead to uncontrolled activation of Wnt5a signal pathways." (PMID 24416340, 2014). "Compared with matched non-malignant tissues, Wnt5a mRNA was upregulated in 21 gastric cancer specimens, whereas downregulated in 6 cases." (PMID 24993819, 2014). "A cancer-promoting function was also shown in UACC 1273 melanoma cancer cells, MKN-74 and MKN-45 gastric cancer cells and in PANC1, HT1080, ImimPc1 and MiaPaca pancreatic cancer cell lines, where overexpression of Wnt-5a promoted cell proliferation and invasion." (PMID 19603030, 2009). "Therefore, the primary aim of this study was to investigate how gastric cancer cells respond to a WNT5A-high environment despite lacking one of the most important WNT5A receptors." (PMID 37722040, 2023). "WNT5A mRNA was shown to be 357-fold higher in primary gastric normal myofibroblasts (gNM) compared to AGS cells and over 800-fold higher in primary gastric cancer–associated myofibroblasts (gCAM) and a pancreatic cancer–associated fibroblast cell line (pCAF2) compared to AGS cells using qRT-PCR." (PMID 37722040, 2023).